TBC1D2B (TBC1 domain family member 2B)
Description:
GTPase-activating protein that plays a role in the early steps of endocytosis.
Synonyms: KIAA1055; NEDSGO
Tractability: Antibody: its Gene Ontology location is reachable by antibodies, with medium confidence. PROTAC: ubiquitination databases record sites on it; its protein half-life has been measured.
Gene: Protein-coding gene on chromosome 15 (77,984,036 to 78,077,724, reverse strand). Ensembl gene ENSG00000167202.
Subcellular location: Early endosome
Subcellular location (Human Protein Atlas): Cytosol
Gene Ontology:
Molecular function: protein binding; GTPase activator activity
Biological process: endocytosis; regulation of cilium assembly
Cellular component: cytosol; early endosome; cytoplasm; plasma membrane; cytoplasmic vesicle
Genetic constraint (gnomAD): Loss-of-function variants: 54 observed, 91.64 expected, observed/expected ratio (o/e) 0.59, 90% interval 0.47 to 0.74. The upper end of that interval is the gene's LOEUF score, 0.74, which puts it in group 3 of 6, group 1 being the genes least tolerant of losing a copy. Missense variants: 1,019 observed, 1,160.2 expected, observed/expected ratio (o/e) 0.88, 90% interval 0.83 to 0.93. Synonymous variants: 468 observed, 450.27 expected, observed/expected ratio (o/e) 1.04, 90% interval 0.96 to 1.12.
Homologues: Orthologues: chimpanzee TBC1D2B (99% identical), pig TBC1D2B (92% identical), rat Tbc1d2b (90% identical), mouse Tbc1d2b (89% identical), guinea pig TBC1D2B (88% identical), macaque TBC1D2B (85% identical), dog TBC1D2B (77% identical), rabbit TBC1D2B (72% identical), tropical clawed frog tbc1d2b (61% identical), zebrafish tbc1d2b (60% identical). Paralogues in human: TBC1D2 (38% identical), TBC1D1 (16% identical), TBC1D9 (15% identical), TBC1D9B (15% identical), TBC1D10B (15% identical), RABGAP1L (14% identical), TBC1D8 (14% identical), RABGAP1 (14% identical), TBC1D8B (14% identical), TBC1D4 (14% identical), TBCK (11% identical), TBC1D10A (11% identical), and 33 more.
Diseases named in the same sentence as TBC1D2B in open-access papers:
TBC1D2B is named in the same sentence as 20 diseases in open-access papers, as found by Europe PMC text mining. Sharing a sentence is not in itself a finding about the gene and the disease. The quoted sentences say what the papers report.
lung carcinoma (4 papers, 2019 to 2025). "Compared with control cells, a reduced amount of biotinylated E-cadherin localized to the cytoplasm of TBC1D2b overexpressing 344SQ and 531LN2 murine lung cancer cells, suggesting that TBC1D2b regulates E-cadherin endocytic processing." (PMID 31719531, 2019). "To study the role of TBC1D2b in lung cancer metastasis we inducibly expressed TBC1D2b or GFP in the murine and human cell lines 344SQ, 531LN2 and H1299." (PMID 31719531, 2019). "Likewise, repression of miR200 and TBC1D2b in lung cancer cells by ZEB1 complex induces E-cadherin endocytosis and endosomal degradation." (PMID 38097578, 2023). "Additionally, Manshouri and colleagues demonstrated that the ZEB1/NuRD complex inhibits TBC1D2b to stimulate E-cadherin internalization and promotes metastasis in lung cancer." (PMID 35884488, 2022).
gingival fibromatosis (2 papers, 2024 to 2025). "Recently, a novel bi-allelic frameshift variant in the TBC1D2B gene was also found in two siblings with gingival fibromatosis, fibrous dysplasia of face, mental deterioration, limb tremors, gait ataxia, and seizures." (PMID 39201553, 2024). "Defective endosomal maturation and E-cadherin internalization as a result of the TBC1D2B mutations result in an increased epithelial-to-mesenchymal transition, uncontrolled cell growth, and subsequent gingival fibromatosis." (PMID 39201553, 2024). "It appears that gingival fibromatosis in patients with TBC1D2B variants is a consequence of disrupted RAB-mediated endocytic trafficking as a result of the altered TBC1D2B protein." (PMID 39201553, 2024). "An extremely rare heterozygous base substitution variant (c.2471A>G) in the TBC1D2B gene was identified in patients 2–4 with hereditary gingival fibromatosis." (PMID 39201553, 2024).
Ramon syndrome (2 papers, 2024 to 2025). "Here, we provide further support for the role of TBC1D2B in Ramon syndrome with the identification a novel homozygous variant in a Thai patient." (PMID 39201553, 2024). "Bi-allelic variants resulting in loss of function of the ELMO2 and TBC1D2B proteins have been reported in Ramon syndrome." (PMID 39201553, 2024). "Exome sequencing identified rare variants in TBC1D2B in both conditions: a novel homozygous variant (c.1879_1880del, p.Glu627LysfsTer61) in a Thai patient with Ramon syndrome and a rare heterozygous variant (c.2471A>G, p.Tyr824Cys) in a Cambodian family with HGF." (PMID 39201553, 2024). "To date, two genes, ELMO2 and TBC1D2B, have been linked to Ramon syndrome." (PMID 39201553, 2024). "With support from mutant protein modeling, our data suggest that TBC1D2B variants contribute to both Ramon syndrome and HGF, although variants in additional genes might also contribute to the pathogenesis of HGF." (PMID 39201553, 2024). "Our finding of a novel homozygous truncating allele in patient 1 (c.1879_1880del; p.Glu627LysfsTer61) adds further support for the alteration in TBC1D2B as a major cause of Ramon syndrome, given that only eighteen cases of this syndrome have been reported since 1967." (PMID 39201553, 2024). "Three additional loss-of-function mutations in TBC1D2B were subsequently reported in separate individuals affected with a neurodevelopmental disorder, gingival overgrowth, cherubism-like lesions, seizures, and ocular abnormalities, consistent with a diagnosis of Ramon syndrome." (PMID 39201553, 2024). "A bioinformatic analysis identified a homozygous single base deletion (c.1879_1880del) in the TBC1D2B gene in the patient with Ramon syndrome (patient 1)." (PMID 39201553, 2024). "However, a more recent study demonstrated that the loss of function of Tbc1 domain family member 2B (TBC1D2B; MIM 619152) was the cause of Ramon syndrome." (PMID 39201553, 2024). "Importantly, we also report a rare heterozygous variant in the TBC1D2B gene together with a novel heterozygous variant in the KREMEN2 gene in three family members with HGF, suggesting an overlap in the pathogenesis of HGF with Ramon syndrome." (PMID 39201553, 2024).
Cognitive impairment (1 paper, 2024). Abnormal cognition is characterized by deficits in thinking, reasoning, or remembering. "Biallelic loss-of-function variants in TBC1D2B have been reported in five subjects with cognitive impairment and seizures with or without gingival overgrowth." (PMID 38374468, 2024).
Epithelial Dysplasia (1 paper, 2024). "Thus, it is hypothesized that aberrant TBC1D2B activity may lead to an increased epithelial-to-mesenchymal transition, degradation of E-cadherin, and subsequent epithelial dysplasia." (PMID 39201553, 2024).
hypertrichosis (1 paper, 2024). Excessive hair growth anywhere on the body. "However, subjects with biallelic TBC1D2B variants did not have hypertrichosis and hypoplastic distal phalanges of fingers and/or toes." (PMID 38374468, 2024).
Overgrowth (1 paper, 2024). Excessive postnatal growth which may comprise increased weight, increased length, and/or increased head circumference. "Together, the TBC1D2B disorder is a progressive neurological disease with gingival overgrowth and mandibular prognathia or cherubism as characteristic associated abnormalities." (PMID 38374468, 2024).
Seizure (1 paper, 2024). A seizure is an intermittent abnormality of nervous system physiology characterized by a transient occurrence of signs and/or symptoms due to abnormal excessive or synchronous neuronal activity in the brain. "Seizures were also found in four patients with homozygous and compound heterozygous variants in the TBC1D2B gene reported in two previous studies but at different ages of onset: two at 19 years, one at 3 months, and one at 32 years of age." (PMID 39201553, 2024).
Zimmermann-Laband syndrome (1 paper, 2024). A rare disorder characterized by gingival fibromatosis, coarse facial appearance, and absence or hypoplasia of nails or terminal phalanges of hands and feet. "Clinical features of subjects with biallelic TBC1D2B pathogenic variants show phenotypic overlap with syndromic neurodevelopmental K+ channelopathies or Zimmermann-Laband syndrome associated with dominant KCNN3, KCNH1, and KCNK4 variants." (PMID 38374468, 2024).
cancer (3 papers, 2019 to 2023). A tumor composed of atypical neoplastic, often pleomorphic cells that invade other tissues. "We find that TBC1D2b suppresses E-cadherin internalization, thus hindering cancer cell invasion and metastasis." (PMID 31719531, 2019).
neurodegenerative disease (2 papers, 2021 to 2024). A disorder of the central nervous system characterized by gradual and progressive loss of neural tissue and neurologic function. "Importantly, defects in autophagy and the endolysosomal system have been associated with neuronal dysfunction and neurodegenerative diseases, raising the possibility that the TBC1D2B-related disease belongs to this group of disorders." (PMID 38374468, 2024). "As TBC1D2B has been shown to positively regulate autophagy, defects in autophagy and the endolysosomal system could be associated with neuronal dysfunction and the neurodegenerative disease in the affected individuals." (PMID 38374468, 2024).
tumor (1 paper, 2019). "We next investigated the functional role of TBC1D2b in tumor cell migration and invasion." (PMID 31719531, 2019).
TBC1D2B also shares sentences with these, for which no sentence is quoted: fibromatosis (1 paper); Gait ataxia (1); gingival hyperplasia (1); gingival overgrowth (1); hepatoma (1); leukemia (1); neurological disease (1); skin cutaneous melanoma (1).